PELI2 (pellino E3 ubiquitin protein ligase family member 2)
Description:
E3 ubiquitin ligase catalyzing the covalent attachment of ubiquitin moieties onto substrate proteins. Involved in the TLR and IL-1 signaling pathways via interaction with the complex containing IRAK kinases and TRAF6. Mediates IL1B-induced IRAK1 'Lys-63'-linked polyubiquitination and possibly 'Lys-48'-linked ubiquitination. May be important for LPS- and IL1B-induced MAP3K7-dependent, but not MAP3K3-dependent, NF-kappa-B activation. Can activate the MAP (mitogen activated protein) kinase pathway leading to activation of ELK1.
Tractability: PROTAC: ubiquitination databases record sites on it.
Gene: Protein-coding gene on chromosome 14 (56,117,814 to 56,301,524, forward strand). Ensembl gene ENSG00000139946.
Subcellular location (Human Protein Atlas): Basal body; Nucleoli; Nucleoplasm; Centriolar satellite; Centrosome; Cytosol; Intermediate filaments
Pathways (Reactome):
Immune System: IRAK1 recruits IKK complex; IRAK1 recruits IKK complex upon TLR7/8 or 9 stimulation; Interleukin-1 signaling
Gene Ontology:
Molecular function: phosphorylation-dependent protein binding; protein binding; ubiquitin protein ligase activity; ubiquitin-ubiquitin ligase activity
Biological process: negative regulation of cGAS/STING signaling pathway; positive regulation of canonical NF-kappaB signal transduction; positive regulation of MAPK cascade; positive regulation of protein phosphorylation; protein K63-linked ubiquitination; protein polyubiquitination; protein ubiquitination; regulation of Toll signaling pathway
Cellular component: cytosol
Genetic constraint (gnomAD): Loss-of-function variants: 20 observed, 34.58 expected, observed/expected ratio (o/e) 0.58, 90% interval 0.41 to 0.84. The upper end of that interval is the gene's LOEUF score, 0.84, which puts it in group 3 of 6, group 1 being the genes least tolerant of losing a copy. Missense variants: 407 observed, 511.95 expected, observed/expected ratio (o/e) 0.8, 90% interval 0.73 to 0.86. Synonymous variants: 221 observed, 199.64 expected, observed/expected ratio (o/e) 1.11, 90% interval 0.99 to 1.24.
Homologues: Orthologues: macaque PELI2 (100% identical), chimpanzee PELI2 (99% identical), pig PELI2 (99% identical), dog PELI2 (98% identical), guinea pig PELI2 (96% identical), mouse Peli2 (95% identical), rat Peli2 (92% identical), tropical clawed frog peli2 (91% identical), rabbit PELI2 (91% identical), zebrafish peli2 (86% identical), Drosophila melanogaster Pli (58% identical), Caenorhabditis elegans peli-1 (45% identical). Paralogues in human: PELI1 (81% identical), PELI3 (71% identical).
Diseases named in the same sentence as PELI2 in open-access papers:
PELI2 is named in the same sentence as 23 diseases in open-access papers, as found by Europe PMC text mining. Sharing a sentence is not in itself a finding about the gene and the disease. The quoted sentences say what the papers report.
gastric cancer (2 papers, 2023 to 2025). A primary or metastatic malignant neoplasm involving the stomach. "Previous research on PELI2 focused on inflammatory responses, and and some studies have also linked PELI2 to leukaemia, gastric cancer, and multiple myeloma." (PMID 40500708, 2025). "PELI2, RGS2 and ENO2 has been poorly reported in relation to liver cancer, whereas PELI2 involved in 28 gene expression characteristics can well predict gastric cancer with lymphatic metastasis." (PMID 37397026, 2023). "It has been proposed that PELI2 could promote the growth and metastasis of gastric cancer cells by regulating vascular endothelial growth factor C, considered as a sensitive predictive tool for lymphatic metastasis in gastric cancer." (PMID 40500708, 2025).
brain tumors (1 paper, 2017). "Also, PELI2 is one of the conserved targets of a brain-enriched microRNA, miRNA-128 which is differentially expressed in brain tumors and neuronal differentiation." (PMID 28792504, 2017).
breast carcinoma (1 paper, 2022). "Importantly, those genes, such as Peli2 and Fhl5, were found to be simultaneously down-regulated in breast cancers." (PMID 35180880, 2022).
colon cancer (1 paper, 2025). "We found that the PELI2 was lowly expressed in a variety of cancers including colon cancer and rectal cancer." (PMID 40500708, 2025). "RT-qPCR and immunohistochemistry showed that PELI2 were reduced in patient colon cancer tissues and even lower in liver metastatic tissues." (PMID 40500708, 2025).
colorectal cancer (1 paper, 2025). A primary or metastatic malignant neoplasm that affects the colon or rectum. "In brief, our study shows that PELI2 inhibits colorectal cancer development by MAPK signaling pathway." (PMID 40500708, 2025). "Transcriptome analysis suggested that PELI2 suppressed colorectal cancer progression via the MAPK signaling pathway." (PMID 40500708, 2025). "Moreover, PELI2 decreased the proliferation, migration and anti-apoptosis of colorectal cancer cells in vitro." (PMID 40500708, 2025). "However, the role of PELI2 in colorectal cancer has not been revealed." (PMID 40500708, 2025).
colorectal tumor (1 paper, 2025). "We also constructed xenograft tumor model to verify colorectal tumor growth slowed down after PELI2 overexpression." (PMID 40500708, 2025). "In the present study, we found that expression level of PELI2 were reduced significantly in colorectal tumors compared with normal tissues." (PMID 40500708, 2025).
Fanconi anemia (1 paper, 2025). Fanconi anemia (FA) is a hereditary DNA repair disorder characterized by progressive pancytopenia with bone marrow failure, variable congenital malformations and predisposition to develop hematological or solid tumors. "In addition, GSEA analysis showed that MUC4 was enriched in Fanconi anemia, GnRH secretion, PPAR signaling, and other pathways; PELI2 was enriched in MAPK, Ras, Wnt, and other signaling pathways." (PMID 38536652, 2025).
Hypertension (1 paper, 2019). The presence of chronic increased pressure in the systemic arterial system. "In addition, PELI2 has been reported to play a role in postmenopausal osteoporosis and hypertension." (PMID 30971501, 2019).
metastatic tumours (1 paper, 2020). "Moreover, ADAM22 expression correlated with known brain metastatic associated in both primary (MOCS1, n = 21, p < 0.05) and metastatic tumours (MOCS1, COL13A1, TLR4, HBEGF and PELI2, n = 21, p < 0.05)." (PMID 33208158, 2020).
multiple myeloma (1 paper, 2025). "In addition, Kaplan-Meier survival analysis revealed that higher expression of PELI2 is associated with a better prognosis of myeloma." (PMID 40500708, 2025).
rectal cancer (1 paper, 2025). A primary or metastatic malignant neoplasm that affects the rectum. "TCGA analysis showed that PELI2 was significantly low-expressed in colon and rectal cancer tissues." (PMID 40500708, 2025).
Sepsis (1 paper, 2021). Sepsis is defined as life-threatening organ dysfunction caused by a dysregulated host response to infection. "miR-128-3p significantly reversed cellular apoptosis as well as inflammation related with ALI via enhancing the expression of PELI2 in MPVECs, which implied that miR-128-3p improved ALI caused by sepsis by suppressing its downstream target PELI2." (PMID 34430706, 2021). "In conclusion, these results implied that miR-128-3p inhibited apoptosis and inflammatory responses in ALI were caused by sepsis by target gene suppression, PELI2." (PMID 34430706, 2021). "Previous studies have verified that PELI2 plays a role in lung injury caused by sepsis, which mechanism might be related to PELI2 activation." (PMID 34430706, 2021). "In conclusion, we found that miR-128-3p exerted effects in protection of sepsis-induced ALI, and it could be achieved by targeting PELI2 with anti-inflammation and anti-injury." (PMID 34430706, 2021). "Further studies showed that miR-128-3p decreased apoptosis as well as inflammatory response in ALI induced by sepsis through negative modification of downstream target PELI2." (PMID 34430706, 2021).
cancer (3 papers, 2021 to 2025). A tumor composed of atypical neoplastic, often pleomorphic cells that invade other tissues. "The role of PELI2 in cancer remains ambiguous due to the heterogeneity of cancer types." (PMID 40500708, 2025). "Based on observations that IL-1β and IL-18 can contribute to AML anti-cancer drug resistance, and based on our data showing enhanced expression of PELI2 gene, mediating IL-1β and IL-18 activation may be a distinct plausible important mechanism by which PELI2 involved in emergence of drug resistance." (PMID 34127725, 2021). "Both genes are connected with other genes notably deregulated in cancer as ANGPTL1, ADAMTSL2, PELI2 and EPCAM." (PMID 41231825, 2025). "These genes were also connected with other genes notably deregulated in cancer as ANGPTL1, ADAMTSL2, PELI2 and EPCAM." (PMID 41231825, 2025).
tumor (2 papers, 2025). "In conclusion, this study is the first to reveal the tumor-suppressive role of PELI2 in CRC." (PMID 40500708, 2025). "In conclusion, overexpression of PELI2 can inhibit tumor formation ability of CRC cells in vivo." (PMID 40500708, 2025). "Xenograft models further indicate that PELI2 overexpression inhibits tumor growth in vivo." (PMID 40500708, 2025). "In this study, we identify PELI2, an E3 ubiquitin ligase, as a potential tumor suppressor in CRC." (PMID 40500708, 2025). "Immunohistochemical staining showed that the PELI2 expression in oePELI2 group tumors was significantly higher than Vector group tumors, and Ki-67 staining confirmed that oePELI2 could reduce proliferation of tumor cells in vivo." (PMID 40500708, 2025). "In order to verify the role of PELI2 on CRC tumor growth in vivo, we constructed nude mouse xenograft tumor model." (PMID 40500708, 2025). "In this study, we reported that PELI2 was down-regulated in CRC and inhibited tumor cell growth for the first time." (PMID 40500708, 2025). "While our findings highlight PELI2’s role in cell cycle and EMT regulation, other pathways may also contribute to its tumor-suppressive effects." (PMID 40500708, 2025).
PELI2 also shares sentences with these, for which no sentence is quoted: infection (2 papers); acute respiratory distress syndrome (1); clear cell renal carcinoma (1); leukaemia (1); liver cancer (1); lung adenocarcinoma (1); pancreatic cancer (1); postmenopausal osteoporosis (1); viral infection (1).